CDIN1 (CDAN1 interacting nuclease 1)
Description:
Plays a role in erythroid cell differentiation.
Synonyms: C15orf41; HH114; MGC11326; FLJ22851
Tractability: PROTAC: ubiquitination databases record sites on it.
Gene: Protein-coding gene on chromosome 15 (36,579,626 to 36,810,248, forward strand). Ensembl gene ENSG00000186073.
Subcellular location: Nucleus; Cytoplasm
Subcellular location (Human Protein Atlas): Nucleoplasm
Gene Ontology:
Molecular function: protein binding
Biological process: erythrocyte differentiation
Cellular component: cytoplasm; nucleus
Genetic constraint (gnomAD): Loss-of-function variants: 22 observed, 33.75 expected, observed/expected ratio (o/e) 0.65, 90% interval 0.47 to 0.93. The upper end of that interval is the gene's LOEUF score, 0.93, which puts it in group 3 of 6, group 1 being the genes least tolerant of losing a copy. Missense variants: 263 observed, 286.1 expected, observed/expected ratio (o/e) 0.92, 90% interval 0.83 to 1.02. Synonymous variants: 106 observed, 108.37 expected, observed/expected ratio (o/e) 0.98, 90% interval 0.83 to 1.15.
Homologues: Orthologues: chimpanzee CDIN1 (99% identical), rabbit CDIN1 (97% identical), pig CDIN1 (96% identical), guinea pig CDIN1 (95% identical), mouse Cdin1 (95% identical), rat Cdin1 (95% identical), tropical clawed frog cdin1 (63% identical), macaque CDIN1 (61% identical), zebrafish cdin1 (60% identical), Drosophila melanogaster CG12713 (32% identical).
Diseases named in the same sentence as CDIN1 in open-access papers:
CDIN1 is named in the same sentence as 6 diseases in open-access papers, as found by Europe PMC text mining. Sharing a sentence is not in itself a finding about the gene and the disease. The quoted sentences say what the papers report.
Congenital dyserythropoietic anemia type I (3 papers, 2021 to 2025). Congenital dyserythropoietic anemiatype I (CDA I) is a hematologic disorder of erythropoiesis characterized by moderate to severe macrocytic anemia occasionally associated with limb or nail deformities and scoliosis. "The CDIN1 gene encodes a novel restriction endonuclease, belonging to the Holliday junction resolvase family, and two missense mutations have been identified to be responsible for autosomal recessive congenital dyserythropoietic anemia type Ib (OMIM #615631)." (PMID 34930369, 2021). "Codanin-1 (CDAN1) is an essential and ubiquitous protein named after congenital dyserythropoietic anemia type I, an autosomal recessive disease that manifests from mutations in CDAN1 or CDIN1 (CDAN1 interacting nuclease 1)." (PMID 40091041, 2025). "Codanin-1 (CDAN1) is an essential and ubiquitous protein named after congenital dyserythropoietic anemia type I (CDA-I), an autosomal recessive disease that manifests from mutations in the CDAN1 or CDIN1 (CDAN1 interacting nuclease 1) gene." (PMID 39149339, 2024).
cardiomyopathy (1 paper, 2023). A disease of the heart muscle or myocardium proper. "Significant differential imbalance between all four phenogroups was found for several SNPs located in genes with known cardiomyopathy links other than DCM such as posterior myocardial infarction, the top 5 hits were EZH1, NIBAN1, C7, CDIN1, and ADPRHL1." (PMID 36631531, 2023).
developmental delay (1 paper, 2021). "10, 11, and 12) of the MEIS2 gene (NM_170676.5) and CDIN1 in two siblings, presenting mild developmental delay and bifid uvula." (PMID 34930369, 2021).
Obesity (1 paper, 2021). Accumulation of substantial excess body fat. "Four of them, CDIN1 (chr15), LINGO1 (chr15), LINC01184 (chr5), and LOC105369911 (chr12), lie within reported GWAS loci related to BMI, body height, and obesity and are located on different chromosomes from rs12040085." (PMID 33957961, 2021).
CDIN1 also shares sentences with these, for which no sentence is quoted: congenital dyserythropoietic anaemia type I (2 papers); diabetes (1).